CD4 (CD4 molecule)
Diseases named in the same sentence as CD4 in open-access papers (continued):
Sharing a sentence is not in itself a finding about the gene and the disease.
infection (continued). "The results show that in the chronic phase of infection, WT mice have a higher number of pulmonic CD4+ T cells compared to that detected in the B cell-deficient μMT and anti-CD20-treated WT mice." (PMID 36888692, 2023). "(c) Are TLR7 expression levels associated with the capacity to maintain CD4+ T cell homeostasis during primary infection?" (PMID 37227774, 2023). "CD40L blockade and Bcl6+CD4+ T cell deficiency both dampen TFH responses yet have opposing effects on control of infection." (PMID 37721965, 2023). "In pathogenic infections, CD4+ T-cell depletion occurs early and persists throughout the infection, despite an increased CD4+ T-cell proliferation." (PMID 36813761, 2023). "Among these, FIV is an important cat pathogen whose infection usually leads to the depletion of CD4+ T cells and causes AIDS-like diseases in cats." (PMID 37376637, 2023). "The outcomes of multivariable logistic regression demonstrated that CD4+ T-cell levels of <300/μL was independent risk factor for early infection." (PMID 37360336, 2023). "This suggests that the risk of infection is significantly increased in the patients with low CD4+ cell counts." (PMID 37138234, 2023). "Conversely, a humoral immune response characterized by the production of anti-inflammatory cytokines, such as IL-10 in VL or IL-4 in CL, by CD4+ T helper cells (Th2) leads to susceptibility to infection." (PMID 37569710, 2023). "The sorted cells were significantly more susceptible to infection than were total blood CD4 + Tm cells, validating the original predictions made by PP-SLIDE." (PMID 36689119, 2023). "CD8+ T cells are essential to control infection as proved by an experiment where mice susceptible to L. major infection were transiently depleted for CD4+ T cells and the CD8+ T cells kept the animals resistant to infection." (PMID 36680003, 2023). "A dysfunctional CD4+ T-cell response during infection was linked to immunopathology after FI-RSV vaccination." (PMID 37896776, 2023). "The aim of the study is to explore the strength of the association between Bh infection risk and CD4+ T cell counts, HIV viral load (VL), and duration of interruption in HARRT." (PMID 37697423, 2023). "Initial infection with the FIVC36 strain typically causes a transient increase in CD4+ T lymphocytes, followed by a shift to CD8+ cells and a gradual decline in CD4+ cells causing a characteristic inversion of the CD4+:CD8+ ratio." (PMID 37112803, 2023). "In HIV infection, DC have been reported to be a potential reservoir site and have been implicated in facilitating infection of CD4 T cell by trans-infection." (PMID 38045254, 2023). "The first PP-SLIDE study was used to define the features of tonsillar CD4 + T cells most susceptible to productive infection [9••]." (PMID 36689119, 2023). "This suggests that most of the plasma virus is produced by infected cells in the tissues, a concept that is consistent with the fact that the activation events that render CD4+ T cells susceptible to infection occur in the secondary lymphoid organs." (PMID 37844236, 2023). "T cells are fundamental for Leishmania immunity, and it is generally accepted that the difference between resistance or susceptibility to infection is associated with the level of expansion of CD4+ Th1 and CD4+ Th2 cells, respectively." (PMID 36680003, 2023). "Since tCre was higher and tNAA/tCre was lower among PHIV subjects, this shows that the severity of infection (indicated by lower CD4 count) was associated with poorer brain metabolic outcomes and more severe gliosis and neuronal loss." (PMID 36937663, 2023). "Further studies that will focus on in-vivo neutralization assays, functionality of T-cell responses (e.g., CD4 vs CD8 responses) as well as monitoring the risk of these patients to infection and/or severe disease are required." (PMID 37051242, 2023).
infection (continued). "This revealed some pathogenic phenotypes associated with infection and critically that vaccination allows maintenance of testicular homeostasis, likely by preventing significant influx of CD4 T cells and promoting IL10 production." (PMID 36799886, 2023). "Moving on, EBV presentation is mediated by HLA-class II alleles before the latent phase of the infection; CD4+ T cells recognize particles presented by MHC-class II in the surface of infected B lymphocytes and eliminate them." (PMID 36844219, 2023). "CCR5 is a coreceptor utilized by HIV/SIV for infection of CD4+ T cells and is closely linked to T cell loss." (PMID 37039653, 2023). "These EVs are enriched in HLA-DR1, CD63, CD9 and are associated with HIV-1 particles, which induce active infection of recipient CD4 T cells through the HIV-1 GP120 receptor." (PMID 36674550, 2023). "Here, we provided the complementary observation that ancestral- or Alpha variant-infection elicit comparable CD4+ T cell responses to ancestral Spike." (PMID 35154116, 2022). "There was a significant decrease in frequency and number of human CD4+ T cells in the blood of both the huNRG and huDRAG-A2 mice at 8 weeks post-infection, which is a hallmark of HIV infection in humans." (PMID 36146734, 2022). "The influence of actin remodeling on HIV infection has previously been demonstrated in CD4+ T cells, where dynamin inhibition has been linked to infection of impaired cells." (PMID 35204813, 2022). "This was associated with higher age, longer infection time, lower CD4+ T cell counts, subtype C infection, or higher titer of C2V3C3-specific antibodies relative to patients that did not develop bNAbs." (PMID 36445130, 2022). "Immune cells called CD4 T cells help the body build immunity to infections caused by bacteria and viruses, or after vaccination." (PMID 35074048, 2022). "Pre-infection plasma SCGFβ (HR = 3.71, 95% CI 1.28–10.77, p = 0.016) and TNFβ (HR = 2.24, 95% CI 1.13–4.45, p = 0.022) levels significantly predicted faster CD4 loss in the bivariate analysis." (PMID 35165387, 2022). "It is well-recognized that a decline in CD4+ cell numbers is associated with attenuation of the cell immune system and an increased vulnerability to being infected with other infections." (PMID 36104731, 2022). "Although current solid organ/bone marrow transplant patients carry elevated risk of infection and medication side effets with current immunosuppressants, ongoing depletion of CD4 and CD40L in humans is also likely to carry some risk." (PMID 36101963, 2022). "Previous studies have found that factors such as a number of organisms consumed, age, sex, nutrition, and CD4 count affect the risk of infection in an individual." (PMID 35457298, 2022). "The interactions between the two infections constitute a major risk factor, not only for the severity of both diseases, but also for leishmaniasis reactivations, especially in people with a CD4+ count < 200 cell/uL." (PMID 36136825, 2022). "Here we showed that pediatric CD4+ T cell responses after infection with an ancestral SARS-CoV-2 variant are age dependent, with reduced capability of the youngest to mount specific responses." (PMID 35911689, 2022). "The ARTRM Q174K was associated with increased viral load and decreased CD4+ cell count, while infection with CRF02_AG was associated with a lower likelihood of Q174K." (PMID 36229577, 2022). "CD4+ T helper cells are crucial components of adoptive immunity, which coordinates in providing immunity against pathogenic infection." (PMID 36238303, 2022). "High CD4+ T cell counts prior to infection were associated with significantly higher rate of CD4+ T cell decline in the first 3 months of infection, likely related to increased HIV replication." (PMID 35165387, 2022). "While HIV-1 is primarily an infection of CD4 + T cells, there is an emerging interest towards understanding how infection of other cell types can contribute to HIV-associated comorbidities." (PMID 36476484, 2022).
infection (continued). "Recently, we have documented that CD8 T cells play a critical role in pathogenicity during the acute phase of LASV infection in STAT1-/- mice, while CD4 T cells play an important role in LASV-induced hearing loss during the chronic phase of infection." (PMID 36289695, 2022). "In this study, we analyzed HIV latency establishment in different CD4+ T cell subsets stimulated with interleukin 15 (IL-15), a cytokine that increases both susceptibility to infection and reactivation from latency." (PMID 35499323, 2022). "Several immunoregulatory molecules and pathways, most notably those associated with IL-10 production, are activated following infection by L. infantum and L. donovani and suppress CD4+ T cell functions." (PMID 35585983, 2022). "High IL‐10 levels in the initial phase of VL lead to susceptibility of infection by decreasing the frequency of multifunctional CD4 T cells." (PMID 35998255, 2022). "When encountering the omicron variant of SARS-CoV-2, memory CD4+ T cell responses wakened by previous infection or vaccination remain intact." (PMID 35615088, 2022). "It is worth mentioning that in an infection model using Toxoplasma gondii, blockade of PD-L1, germline deletion of PD-1, or PD-1 deficiency in Tregs resulted in reduced pathogen-specific CD4+ T cell responses during infection." (PMID 35666747, 2022). "We detected a WT S-reactive CD4+ T-cell response with low avidity at disease onset, implying a failure of cross-reactivation upon infection with the alpha variant." (PMID 35145522, 2022). "We also found evidence of cross-strain protection against pH1N1 infection associated with pre-existing sH1N1-specific CD4 and CD8 T cell responses." (PMID 35858844, 2022). "Mice deficient in the CD4+ T cell subset and Th1 cytokines were associated with a rapid progression to infection-related death." (PMID 36296351, 2022). "In this work, we report that inhibition of sphingosine kinases reduces the susceptibility of CD4 T cells to infection primarily via modulation of SAMHD1 phosphorylation." (PMID 35412343, 2022). "The neutralizing-antibody response has been previously associated with viral load, CD4+ T cell count, viral diversity, and infection time." (PMID 36445130, 2022). "In this regard, the inability of the viral Envs of these patients to efficiently bind to CD4 and fuse is related to the deficient viral transmission and infection, which correlates with a very poor viral evolution and diversity." (PMID 35401460, 2022). "We also found that only a minority of Spike-specific CD4+ T cells targets regions mutated in Alpha, Beta and Delta variants, both after natural infection and vaccination." (PMID 35154116, 2022). "In unadjusted models, PWH with CD4 cell count less than 350 cells/μL had a higher risk of severe infection than PWoH (HR, 2.00; 95% CI, 1.26-3.02)." (PMID 36227594, 2022). "This earlier spread to dendritic cells and T cell priming happens despite strain 4334 inducing fewer inflammatory cells to the lung early in infection and is associated with accelerated priming of antigen-specific CD4 T cells." (PMID 35695454, 2022). "In the early stages of the infection, a hyper-inflammatory state is followed by an immunosuppressed state, and this is potentially associated with a decrease in CD4 + and CD8 + T cells." (PMID 34463916, 2022). "Pneumocystis is another opportunistic fungus that causes infection under immunodeficiency, especially of CD4+ T cells and B cells." (PMID 36177012, 2022). "This infection is mainly characterized by massive CD4+ T cell depletion in the intestinal mucosa, which then affects blood and lymphoid CD4+ T cells, thus causing sustained systemic immune activation and inflammation." (PMID 35682832, 2022). "The role of Th17 in protection is potentially explained by the ability of this pathway to elicit innate lymphoid cells and multipotent progenitor type 2 cells early in infection that subsequently promote CD4+ Th2 cells and associated cytokine expression." (PMID 35798788, 2022).
infection (continued). "In human immunodeficiency virus, homozygosity for the short allele of TIM-1 was associated with natural protection from infection and a lower rate of virus replication in CD4+ T lymphocytes." (PMID 35384693, 2022). "Severe immunosuppression with below 200 CD4 cells/μl increases the viral load that affects the immune system, posing patients to the risk of infection with microsporidia and other opportunistic pathogens." (PMID 34983416, 2022). "Our data provide important evidence for a certain cross reactivity of the pediatric CD4+ T cell response after infection with an ancestral SARS-CoV-2 variant to mutations in the Spike domain." (PMID 35911689, 2022). "Taken together, this longitudinal study of CD4 T cell dynamics confirmed rapid loss of CD4 T cells in both peripheral blood and tissues following pathogenic SIVmac251 infection." (PMID 36000842, 2022). "HIV is a retrovirus whose infection gradually deteriorates the functionalities of the immune response, as it induces a slow decrease of the CD4+ T cell pool and causes major gaps in the immune repertoire." (PMID 36552017, 2022). "In our study, 2 of the pre-infection plasma cytokines (SCGFβ and TNFβ) significantly predicted faster CD4+ T loss." (PMID 35165387, 2022). "The Il18ra-/- mouse lineage was previously shown to be very susceptible to infection with T. cruzi, and display lower numbers of CD4+GzB+ and CD4+PRF+ T cells with cytotoxic potential." (PMID 35670567, 2022). "Our previous study revealed that IL-10 antagonized the control of Mtb infection by promoting the generation of vasculature-associated CD4+ T cells with reduced ability to migrate into the lung parenchyma and induce control of infection." (PMID 35935958, 2022). "Taken together, these findings demonstrate that the CD4+ T cells in pediatric and adult ECs share similar phenotypes, in which they are less susceptible to infection and exhaustion." (PMID 35911681, 2022). "Yet, captive SIVcpz-infected chimps also displayed reduced CD4+ T-cell abundance and disruption of secondary lymphoid tissue architecture typically found in pathogenic infection." (PMID 36713371, 2022). "Of note, the preservation of PD1+CXCR5+CD4+ T cells early during infection has been linked with antibody responses evolving towards broad neutralization." (PMID 35410989, 2022). "These three chemokines bind CCR5, the co-receptor for HIV entry, thus blocking the infection of new HIV susceptible CD4 target cells." (PMID 35746615, 2022). "For instance, in case of infections mediated by lymphtrophic viruses (e.g., human immunodeficiency virus, HIV), Tregs limit hyperactivation of effector CD4+ T cells, thereby indirectly making them less susceptible to infection." (PMID 36016952, 2022). "Over time, the general trend with FIV infection is that both CD4+ and CD8+ T lymphocyte numbers gradually decline, causing progressive dysfunction of the immune system until cats enter the clinical phase of FIV infection." (PMID 35578381, 2022). "OROV infection has also been studied in human blood mononuclear cells, and results demonstrated that T CD4+ lymphocytes (Jurkat cells) were more susceptible to infection than other lymphoid lineages." (PMID 36298749, 2022). "Fewer associations with CD4:CD8 ratio > 180 days post infection were observed, with IL-10 and stromal cell-derived factor-1 alpha (SDF-1α) being significant in bivariate analysis." (PMID 35165387, 2022). "The results of bivariate Cox proportional hazards regression model analyses showed that age, education level, route of infection, baseline CD4, and current WHO clinical stage were associated with death after HARRT (P < 0.05)." (PMID 36249590, 2022). "Opportunistic infection rates were linked to low hemoglobin levels (<10 mg/dl), low CD4 counts or percentages, WHO clinical stages III and IV, and non-users of CPT." (PMID 36536709, 2022).
infection (continued). "The primary target of HIV infection is CD4+ T cells, resulting in the massive loss of CD4+ T cells during the early stage of infection, especially in the lymphoid tissue that is associated with the gut." (PMID 35746741, 2022). "Broad and elite neutralization was associated with longer infection time, subtype C, lower CD4+ T cell counts, higher age, and higher titer of C2V3C3-specific antibodies relative to failure to develop bNAbs." (PMID 36445130, 2022). "A previous study found that HIV-infected individuals with CD4+ T-cell counts below 200 cells/μl had a higher risk of TM infection." (PMID 36439143, 2022). "In studies of cord blood from sex-discordant twins born to HIV-uninfected mothers, cord blood CD4+ T-cells were indeed more activated in females than males and also were more susceptible to in vitro infection by HIV." (PMID 35634290, 2022). "Our results are also confirmed by previous data obtained by us and others with regard to murine E. multilocularis infections in which mice were treated with CD4-depleting antibodies or subjected to MHC-II deficiency prior to infection." (PMID 36046744, 2022). "We found that a protective response was associated with proliferating, antigen-specific IFN-γ+ TNF+ CD4+ T cell cells, which were prominent in patients who cleared the infection." (PMID 36439147, 2022). "WHO continues to expand the collection of anonymised clinical data, including on other variables of interest (eg, vaccination status, re-infection, variants, therapeutics, CD4 cell counts, and viral load)." (PMID 35561704, 2022). "As it was previously shown that low RBD-specific CD4 T cells response was associated with low neutralizing antibodies at 3- and 8-months post-infection, it was important to correlate these two parameters at the post-vaccination timepoint." (PMID 36544780, 2022). "Susceptibility to infection, latency establishment, and reactivation differ in the distinct CD4+ T cell subsets." (PMID 35499323, 2022). "With the increasing environmental complexity and pathogen diversity, CD4+ T cells differentiate into a specific IFN-γ-secreting Th1 cell subset to resist intracellular pathogenic infections." (PMID 36282845, 2022). "The increased infection in CD4+ T cells stimulated with IL-15 was associated with an almost 10-fold increase in the phosphorylation of SAMHD1 on threonine 592 that abrogates its restriction activity." (PMID 35499323, 2022). "We detected comparable frequencies of ancestral (Wuhan strain) Spike-reactive CD4+ T cells in subjects with history of ancestral- or Alpha-variant infection." (PMID 35154116, 2022). "Our data thus illustrate the more important role of CD4+ T cell response in the control of acute infection than in the control of recurrent infection of P. chabaudi, which was closely associated with the frequency change of CD4+ T cell subsets." (PMID 35250958, 2022). "Many previous studies have shown that a reduction in the number of CD4+ T cells in shock patients induces severe immunosuppression and is associated with high mortality and secondary infection rates." (PMID 35572554, 2022). "An increase in the frequency of CD4+IFNγ+ T cells was observed at the site of infection both in mice genetically deficient for c-MET in neutrophils and in the lesion of mice treated with the c-MET inhibitor capmatinib." (PMID 35041723, 2022). "This GK1.5 regimen completely eliminated CD4+ TRM cell accumulation, demonstrating that this hallmark of experienced lungs requires CD4+ T cells during the initial infections." (PMID 35133985, 2022). "In contrast, CD4+ T cells selectively differentiate into IL-4-producing Th2 cells or IL-17-producing Th17 cells to resist infections caused by extracellular parasites or bacteria." (PMID 36282845, 2022). "In both B6 (normal levels of IL-10) and pMT-10 (high levels of IL-10) BCG-vaccinated mice, the control of infection was associated with a rapid accumulation of Ag85b-specific CD4+ T cells in the lungs." (PMID 35935958, 2022).